ALB (albumin)
Diseases named in the same sentence as ALB in open-access papers (continued):
Sharing a sentence is not in itself a finding about the gene and the disease.
Cirrhosis (continued). "Its clinical relevance is exemplified by the albumin–bilirubin (ALBI) score, a validated prognostic index in cirrhosis, transplantation, and other chronic liver conditions." (PMID 41601806, 2026). "INR, bilirubin, creatinine, and CRP levels increased significantly from compensated cirrhosis to ACLF (p < 0.05), whereas hemoglobin and albumin levels decreased significantly with advancing severity (both p<0.001)." (PMID 41200179, 2025). "These clinical‒microbiome associations are consistent with recent multicenter findings, which identified albumin and the INR as key covariates of microbiome composition in cirrhosis patients." (PMID 41239524, 2025). "Albumin and CRP are serological inflammation-based markers and involved in the progression of cirrhosis." (PMID 41149065, 2025). "The primary finding of the present study was that serum albumin and ammonia levels were robust factors for the development of OHE in geriatric cirrhosis." (PMID 40928524, 2025). "The second finding was that the sHE score, comprising only serum albumin and ammonia levels, was a useful index for predicting the development of OHE in geriatric cirrhosis." (PMID 40928524, 2025). "Valine, HDL_p, Albumin and Total Bilirubin were found to be significantly different both in patients with cirrhosis vs HCC and in patients with HCC and cirrhosis with CPS A vs B/C." (PMID 40183893, 2025). "Conversely, serum albumin levels were slightly lower in the HCV group than in the control group, and significantly lower in the HCC and cirrhosis groups than in both the HCV and control groups." (PMID 39844891, 2025). "As both ALP and ALB are key liver function indicators, we specifically examined the effect of APAR on IS patients with hepatitis or cirrhosis in our subgroup analysis." (PMID 40371078, 2025). "The findings of this study imply that response-guided midodrine and weekly albumin therapy, when combined with SMT, improve patients' overall survival, ascites control, and fewer complications in cirrhosis patients." (PMID 39912014, 2025). "The ALBI index was inversely correlated with albumin (−0.962 in NALC), which effectively stratifies liver dysfunction severity, particularly in compensated cirrhosis." (PMID 40647574, 2025). "These include male gender, age, obesity, years with cirrhosis, family history of liver cancer, baseline alpha-fetoprotein (AFP), albumin, and AST." (PMID 39982238, 2025). "Liver function tests indicated significantly lower albumin and significantly higher ASAT, GGT, alkaline phosphatase, and total bilirubin levels in the cirrhosis group (p-value < 0.001 for all)." (PMID 40364106, 2025). "Based on the univariate logistic regression analyses, the following data were selected for further analysis: gender, BMI, cirrhosis, baseline HBsAg, baseline HBeAg, baseline HBV DNA, ALT, AST, GGT, albumin, AFP, and HGB." (PMID 39702655, 2025). "Taken together, these analyses confirm that classical clinical markers—particularly albumin, supported by INR—remain the dominant predictors of cirrhosis severity." (PMID 41295297, 2025). "Albumin is part of ALBI, EZ-ALBI, mALBI, PNI, and GPS and is a well-known highly prognostic parameter in patients with cirrhosis." (PMID 40059970, 2025). "The features that were retained included age, AFP, HVB, liver failure type, cirrhosis, DBIL, TBIL, CRP, retinol, pre-albumin, platelets, PT, cholinesterase, TT, and monocytes." (PMID 41220690, 2025). "Albumin was negatively correlated with INR (ρ = –0.37) and with bilirubin fractions (ρ = –0.42 and –0.44), patterns consistent with advanced cirrhosis." (PMID 41295297, 2025). "In the present study, serum albumin and ammonia levels were independent factors for OHE development in geriatric cirrhosis, and the sHE score, composed of these factors, was also shown to be useful for predicting OHE development in the geriatric population." (PMID 40928524, 2025).
Cirrhosis (continued). "This systematic review aims to evaluate the efficacy of albumin infusion in preventing acute kidney injury and delaying HCC progression among patients with decompensated cirrhosis." (PMID 41140983, 2025). "Importantly, there was a degree of consistency across trials: albumin use was repeatedly associated with reduced risk of AKI, hyponatremia, and paracentesis-induced circulatory dysfunction (PICD), reinforcing its role as a cornerstone in managing decompensated cirrhosis." (PMID 41140983, 2025). "Albumin, triglycerides, TC, white blood cell count, and platelets increased significantly (p<0.001, p<0.05) in Steatosis and MASH compared to cirrhosis and HCC, respectively." (PMID 41220919, 2025). "Independent factors included cirrhosis, PVP hypo-enhancement, elevated AFP level (> 40 ng/mL), and lowered albumin level (< 29 g/L) which was similar with that in other studies." (PMID 41105281, 2025). "The results of our study show that models combining baseline variables that include albumin, INR, and platelet count were strongly associated with decompensation events and could estimate 30-day risk of adverse liver-related outcomes in patients with cirrhosis due to MASH or viral hepatitis." (PMID 40591542, 2025). "Age, gender, cirrhosis at baseline, alcohol abuse, platelets, INR, and total bilirubin and albumin were the factors related to HCC development in unadjusted univariate analysis." (PMID 39061161, 2024). "Between week 10 and 15, significant increases in total bilirubin and ammonia were observed, and ascitic fluid exhibited a serum-ascites albumin gradient (SAAG) higher than 1.1 g/dl, indicating the presence of decompensated cirrhosis." (PMID 39188716, 2024). "In healthy individuals, albumin can bind to pro-inflammatory molecules in the serum and immunosuppressive mediators (PGE), whose serum concentrations are elevated in cirrhosis." (PMID 39337069, 2024). "In a real-world, multicenter study in Japan, in patients with compensated cirrhosis at SVR12, the serum albumin level improved 18% at EOT and 27% at SVR1223." (PMID 37268672, 2023). "Liver cirrhosis patients had significantly higher levels of AST, T.Bil, ALP, creatinine, and INR and lower levels of ALB and PLT than non-cirrhosis patients." (PMID 37861502, 2023). "In this study, 126 patients with cirrhosis and SBP were recruited either to receive cefotaxime (63 patients) or cefotaxime and albumin (63 patients)." (PMID 37218881, 2023). "Univariate and multivariate analysis showed that tumor size ≥5 cm (P < 0.001), ALB <35 g/L (P < 0.001), PIVKAII ≥20 mAU/mL (P = 0.001), cirrhosis (P < 0.001), and tumor RECIST response (P < 0.001) were independent risk factors of OS." (PMID 37197414, 2023). "Conversely, PBC patients who did not exhibit hyperlipidemia tended to be older, had lower levels of serum ALB and PLT, and experienced higher rates of cirrhosis and mortality, suggesting a more severe and progressive form of the disease." (PMID 38027142, 2023). "Considering the strong correlation between albumin and inflammatory cytokines, CAR is a useful indicator for patients with cirrhosis." (PMID 36983211, 2023). "Serum levels of ALB, TP, PLT, and Hb were lower in the HCC and cirrhosis groups than in the hepatitis and normal control groups." (PMID 37189543, 2023). "Decompensated cirrhotic had lower platelet and serum albumin levels and higher serum bilirubin, AST, INR, and creatinine compared to compensated cirrhosis (p < 0.05)." (PMID 37304826, 2023). "At the same time, there was no statistical difference in other factors (age, gender, BMI, cirrhosis, hepatitis B, ASA score, ALB, PT, PLT, AFP, CEA, CA19-9, CA12-5, anatomical liver resection, the extent of resection, major sizes, multiple tumors)." (PMID 37032348, 2023).
Cirrhosis (continued). "The ANSWER trial, which included patients with stable decompensated cirrhosis and grade 2 and 3 ascites (median MELD score~12), showed a 38% decrease in the mortality hazard ratio and better ascites management with albumin supplementation." (PMID 38139434, 2023). "Continued follow‐up of his cirrhosis has shown decreasing transaminases, stable INR, normal albumin, and a continued thrombocytopenia." (PMID 36636598, 2023). "PBC patients with NAFLD had lower proportions of serum ALB<LLN, PLT<LLN, anti-Ro52-positive, and cirrhosis than those in the control group (all P<0.05)." (PMID 38027142, 2023). "On the other hand, albumin (ALB), a well-established surrogate of hepatocellular synthesis, displayed only a moderate difference between patients with cirrhosis and controls." (PMID 36652164, 2023). "Another essential application of albumin is in the management of AKI, which is prevalent in decompensated cirrhosis." (PMID 38139434, 2023). "Patients with decompensated cirrhosis (CPS B/C), ESLD (MELD ≥ 15), as well as CSPH (HVPG ≥ 10 mm Hg) had significantly higher levels of sAxl, Gas6, and their albumin ratios." (PMID 37532736, 2023). "A binominal logistic regression was performed to ascertain the association of baseline paraclinical data (gender, age, rural/urban origin, cholesterol level, AFP, AST, ALT, GGT, BLBt, Albumin, PT (INR), and PLT levels) with the likelihood to have cirrhosis." (PMID 38138039, 2023). "In the open label randomized trial evaluating long-term albumin administration in decompensated cirrhosis (ANSWER), patients received either standard medical treatment with albumin or standard medical treatment alone." (PMID 39132612, 2023). "In patients with decompensated cirrhosis at SVR12, similar improvement in the albumin level was seen." (PMID 37268672, 2023). "Non-cirrhosis CLD patients had a statistically higher level of serum sodium, creatinine, albumin, alanine aminotransferase, and INR than cirrhosis CLD patients." (PMID 34822057, 2022). "Treatment with antibiotics and albumin have reduced the mortality in case of infection, but antibiotics should be prescribed with caution given the increasing prevalence of MDRO in cirrhosis patients." (PMID 36926073, 2022). "Male gender, age, cirrhosis, HBV genotype C, high direct bilirubin, low albumin, high alpha-fetoprotein, and low platelet count were also identified as significant risk factors for HCC." (PMID 35805045, 2022). "The percentage of serum bilirubin >ULN [68.3% vs. 47.9% (cluster 4, Pc=0.04)], serum albumin <LLN [84.6% vs. 65.6% (cluster 3, Pc=0.01)] and cirrhosis [69.2% vs. 38.4% (cluster 3, Pc<0.0001)] were higher compared with those noted in the other clusters." (PMID 36685575, 2022). "Regarding 6-week mortality, our analysis showed that it correlated with FABP2, albumin, CRP levels, severity of liver disease, and the presence of severe cirrhosis-related complications, including portal vein thrombosis and hepatocellular carcinoma." (PMID 35308545, 2022). "The strongest associations were found between infection and age, male, taking alcohol, diuretics, HE, HS, cirrhosis, long-time bed, mechanical ventilation, PTA, ALT, ALB, TC, eGFR, Hb, PLT, MELD scores and ACLF grade." (PMID 35811816, 2022). "Among cirrhosis patients with SBP, IV albumin can increase the mean arterial pressure (MAP), and decrease the serum renin and heart rate (HR), thus showing a significant improvement in the circulatory dysfunction among cirrhosis patients." (PMID 36721617, 2022). "The results demonstrated that sex, age, ECOG performance status score, presence of cirrhosis, clinical T stage, Child-Pugh class, alpha-fetoprotein (AFP) levels, albumin (ALB) levels, and haemoglobin (HGB) levels were significantly related to the OS rate." (PMID 34126955, 2021). "This score comprises five variables, namely, age, albumin, bilirubin, HBV DNA level and absence/presence of cirrhosis, with a possible score ranging from 0 to 44.5." (PMID 34372539, 2021).
Cirrhosis (continued). "The two groups differed in many baseline characteristics, including age, Child–Pugh score, BCLC stage, tumor size, cirrhosis, HBV e antigen (HBeAg) positivity, platelets, total bilirubin, albumin, and prothrombin time." (PMID 34885118, 2021). "Furthermore, besides the decrease in serum albumin level, the molecular structure of albumin undergoes extensive damage in decompensated cirrhosis due to systemic inflammation and oxidative stress, leading to a decline in albumin functions along with the increasing severity of cirrhosis." (PMID 34575311, 2021). "In patients with decompensated cirrhosis and patients with acute-on-chronic liver failure (ACLF), the binding efficiency of albumin for many of its ligands is significantly reduced." (PMID 34836265, 2021). "These factors included age, gender, platelet counts, serum TB, AST, ALT, albumin, AFP level, presence of cirrhosis, tumor size and BCLC stage." (PMID 34045534, 2021). "In patients with advanced fibrosis or cirrhosis due to ALD, serum albumin levels, coagulation function profiles, bilirubin levels, and white blood cell counts should also be collected to determine the severity of the liver injury." (PMID 34068269, 2021). "A month later, his liver function deteriorated (ALT: 33 IU/L, AST: 329 IU/L, ALB: 24.9 g/L, TBIL: 16.6 μmol/L, PT: 13.4 s, massive ascites), and the cirrhosis was classified as Child-Pugh 9 and ALBI grade 3." (PMID 35187075, 2021). "The Cirrhosis Acute GastroIntestinal Bleeding (CAGIB) score also includes four laboratory variables (i.e., total bilirubin [TBIL], albumin, serum creatinine [Scr], and alanine aminotransferase [ALT])." (PMID 33892649, 2021). "In patients with decompensated cirrhosis and ascites, seven RCTs compared TIPS to LVPs plus albumin, the standard of care for patients with RA, showing a superior efficacy in controlling ascites in all of them." (PMID 34830508, 2021). "The two groups were similar with regard to age, sex, cirrhosis, hepatitis viral status, Child–Pugh score, ECOG status, major lesion size, albumin, total bilirubin, ALT and PT." (PMID 33627697, 2021). "In a study of HAS administration in patients with cirrhosis and infections other than SBP, patients receiving albumin were less likely than controls to develop new bacterial infections during the follow-up period (9.8% vs. 24.6%, respectively; p < 0.03)." (PMID 33925831, 2021). "Liver biochemistry analyses, including alanine aminotransferase (ALT), aspartate transaminase (AST), total bilirubin (TBIL), γ-glutamyl transferase (GGT), alkaline phosphatase (ALP), and albumin (ALB), showed alterations in patients with cirrhosis." (PMID 34321090, 2021). "Although serum albumin was included in the CU-HCC score as a predictor, theoretically compensating for the misclassification of cirrhosis by clinical criterion, the predictive performance of CU-HCC was still poor in this subgroup." (PMID 34513751, 2021). "Accordingly, a higher proportion of patients who succumbed to post-treatment mortality had cirrhosis, history of cancer, ascites, high FIB-4 scores, low albumin levels, low hemoglobin levels, and poor renal function." (PMID 33777520, 2021). "Multivariable analysis identified albumin, cholinesterase, INR, and platelets as independent predictors of cirrhosis." (PMID 33526976, 2021). "Previous studies have demonstrated that nutritional support significantly improved serum albumin levels and decreased MELD scores, particularly in Child–Pugh B patients compared to patients with Child–Pugh A cirrhosis." (PMID 34022800, 2021). "Such an improvement, along with an improvement in liver function parameters, such as albumin level, bilirubin level, or prothrombin time, indicates that a beneficial effect can be achieved after SVR among patients with cirrhosis." (PMID 34830518, 2021).
Cirrhosis (continued). "Indeed, hepatocytes isolated from livers of rats with cirrhosis cultured for 72 h on low stiffness ameliorated their functionality with respect to those cultured at higher stiffness, as shown by both mRNA markers and in vitro urea and albumin synthesis and release." (PMID 32939447, 2020). "In relation to cirrhosis, together with gender (OR 5.612, P = 0.041), age (OR 1.061, P = 0.047), HBV DNA (OR 0.619, P = 0.022) and albumin (OR 0.909, P = 0.026), PTX3 (OR 1.671, P < 0.001) was an independent risk factor for HCC." (PMID 33219288, 2020). "Liver diseases associated with impaired protein synthetic function, such as cirrhosis and acute liver failure, result in reductions in VDBP and ALB levels." (PMID 33151930, 2020). "No statistically significant change was detected in patients with Child A cirrhosis, but statistically significant increases in albumin and statistically significant decreases in INR and MELD scores were detected in patients with Child B cirrhosis." (PMID 32093441, 2020). "The calculated prognostic liver scores MELD-XI, MELD-Albumin, and ALBI scores were significantly higher in patients without Fontan palliation indicating more advanced stages of liver fibrosis/cirrhosis." (PMID 33490119, 2020). "We highlight the coexistence of cirrhosis with celiac disease and change in MELD-Na and albumin levels after a gluten-free diet." (PMID 32582496, 2020). "An INR decrease and albumin increase was obtained in the study population as a whole, and a decrease in MELD scores was achieved in patients with Child B cirrhosis." (PMID 32093441, 2020). "In contrast, damaged albumin isoforms accumulate in the vascular compartment, as witnessed by the significant amounts of HNA1 and HNA2 commonly found in patients with cirrhosis [60••]." (PMID 32837825, 2020). "Patients with high PNI-ALBI grade had a higher incidence of larger tumor size (≥2.5 cm), ascites, splenomegaly, cirrhosis, AFP, lower albumin, and higher total bilirubin compared with low PNI-ALBI grade." (PMID 33240907, 2020). "In this research, we highlight the coexistence of cirrhosis with celiac disease and change in MELD-Na and albumin levels after a gluten-free diet." (PMID 32582496, 2020). "As such, these patients require stricter liver enzyme control, albumin levels, and coagulation status throughout their lives, and imaging tests, such as abdominal ultrasound or fibroscan, that allow for early detection of abnormalities suggestive of cirrhosis could even be considered." (PMID 33287251, 2020). "The HCC stage (P = 0.018) and prevalence of cirrhosis (P < 0.001) were significantly higher in the immunotherapy group, and the serum levels of AST, albumin, and total bilirubin were significantly different in the two groups (all P < 0.05)." (PMID 31151419, 2019). "The five most important variables for distinguishing patients’ cirrhosis progression are as follows: APRI, PLT, AST ratio, ALB, AST/ALT." (PMID 30608929, 2019). "The aim of this review is to assess the effectiveness of intravenous albumin therapy to prevent SBP, renal dysfunction and death in adults with cirrhosis." (PMID 30700489, 2019). "Meta-analysis of 3 studies found that albumin infusion significantly improved overt HE (OR=2.40, P=0.04).Conclusions: Based on the results of our retrospective study and meta-analysis, albumin infusion might prevent from the occurrence of overt HE and improve the severity of overt HE in cirrhosis." (PMID 31596729, 2019). "The serum levels of ALT, TBIL, PT, ALB and HBV DNA showed a difference between CHB patients and HBV-related cirrhosis patients (P < 0.05)." (PMID 31200663, 2019). "Parameters representing the liver function, such as bilirubin, albumin, Gamma-glutamyl-transferase (GGT), and INR, as well as the thrombocyte count, were significantly different in the cirrhosis group." (PMID 29897895, 2018).